KDM6B (lysine demethylase 6B)
Diseases named in the same sentence as KDM6B in open-access papers (continued):
Sharing a sentence is not in itself a finding about the gene and the disease.
cervical carcinoma (11 papers, 2013 to 2025). A carcinoma arising from either the exocervical squamous epithelium or the endocervical glandular epithelium. "To address this issue, we first investigated whether ectopic KDM6B expression may rescue the loss of viability caused by KDM6A depletion in CaSki cervical cancer cells." (PMID 28968467, 2017). "These analyses suggest that KDM6A, KDM6B, and RRM2 help cervical cancer cells tolerate HPV E7-associated replication stress independently of TLS gene expression, highlighting the substantial investment that cells commit to mitigating this stress." (PMID 36266721, 2022). "For example, KDM6B induces the expression of cervical cancer marker p16INK4A and promotes the proliferation of cancer cells." (PMID 34001062, 2021). "KDM6B overexpression in cervical cancer is mediated by HPV, and its suppression reduces proliferation." (PMID 31766427, 2019). "Most remarkably, HPV E7 expressing cells, including some cervical carcinoma cell lines become acutely “addicted” to KDM6B and p16INK4A expression." (PMID 28968467, 2017). "Knockdown of either KDM6A or KDM6B in HPV+ cervical carcinoma cell lines not only reduced p16 expression, but also induced cell death." (PMID 29069809, 2017). "Given the result that KDM6A as well as KDM6B expression is essential for viability to cervical carcinoma cells, KDM6 inhibition should be evaluated as a therapeutic modality for some human cancers." (PMID 23673719, 2013). "Interestingly, knockdown of KDM6A or KDM6B in HPV+ cervical cancer cell lines induces cell death and E7 expression induces a KDM6B dependence for cell growth." (PMID 35408843, 2022). "Hence, it was surprising that KDM6A as well as KDM6B depletion dramatically inhibited viability of the HPV16 positive CaSki cervical carcinoma line." (PMID 23673719, 2013). "To reinforce the clinical implications of our findings, we obtained cervical cancer samples to confirm the expression of UTX (KDM6A) and JMJD3 (KDM6B)." (PMID 38576048, 2024).
diabetes (11 papers, 2017 to 2025). "When we compared offspring exposed to late-gestation diabetes born to dams on control vs. a HF diet, a lysine demethylase enzyme-encoding gene, Kdm6b, was associated with significant H3K27me3 loss, suggesting potential upregulation of this enzyme." (PMID 28425976, 2017).
neuroblastoma (11 papers, 2019 to 2025). Neuroblastoma (NB) is the most common solid, extracranial childhood tumor. "JMJD3 is highly expressed in neuroblastoma, where its encoding gene KDM6B is marked by epigenetic modification characteristic for active transcription." (PMID 40253363, 2025). "We found that lower KDM6B expression is significantly associated with reduced event-free survival of neuroblastoma patients, with high-risk neuroblastoma tumors, and with advanced tumor stages." (PMID 30631055, 2019). "In agreement with these experimental data, we found that higher HOXC9 mRNA expression is significantly associated with higher KDM6B mRNA expression in primary neuroblastoma tumors." (PMID 30631055, 2019). "We show that KDM6B is downregulated in neuroblastoma stem-like cells and in poorly differentiated, high-risk neuroblastoma tumors." (PMID 30631055, 2019). "In summary, our study provides clinical and experimental evidence for KDM6B as an epigenetic onco-suppressor in high-risk neuroblastoma by activating a neuronal differentiation program." (PMID 30631055, 2019). "Taken together, these results suggest that KDM6B might function as an epigenetic onco-suppressor in the pathogenesis of high-risk neuroblastoma." (PMID 30631055, 2019). "To determine whether high expression of KDM6B in neuroblastoma is associated with active epigenetic modifications, we investigated the epigenetic landscapes at the genomic loci of KDM6B, KDM6A, and UTY in seven primary human neuroblastoma tissues sequenced at St." (PMID 34893606, 2021). "Thus, high KDM6B expression is associated with neuroblastoma differentiation." (PMID 30631055, 2019). "Consistently, the expected H3K27me3 recovery upon KDM6B inhibition is also counterbalanced by the decrease in EZH2 expression in neuroblastoma." (PMID 41085408, 2025). "KDM6B has been reported to be downregulated in neuroblastoma stem-like cells and to have tumor-suppressive functions." (PMID 37218871, 2023). "Its overexpression reduces proliferation while increasing genes for differentiation, indicating the control of neuroblastoma cell differentiation by a KDM6B demethylase activity-dependent epigenetic mechanism." (PMID 37218871, 2023). "Taking into account the transcriptional regulation mechanism, KDM6B can also achieve tumor suppression via the same way in certain cancers, such as neuroblastoma sphere-forming cells and squamous cell carcinoma cells." (PMID 35783266, 2022). "In neuroblastoma, KDM6B is upregulated by retinoic acid via HOXC9 to remove the repressive chromatin marker H3K27me3 and induce neuronal differentiation, thus inhibiting cell proliferation and tumorigenicity." (PMID 35783266, 2022). "We further validated the importance of KDM6B in neuroblastoma by assessing colony formation after knocking down KDM6B with four different siRNAs in BE2C cells (with MNA) and SK-N-AS cells (with high C-MYC activity)." (PMID 34893606, 2021). "To specifically investigate the conclusion that high E2F activity serves as a biomarker for sensitivity to KDM6B inhibition in neuroblastoma, we categorized neuroblastoma cell lines into two groups according to their IC50 to GSK-J443." (PMID 34893606, 2021). "In summary, we have defined a chromatin-dependent mechanism of action of KDM6B inhibition that modulates the CDK4/6-pRB-E2F pathway in neuroblastoma." (PMID 34893606, 2021). "In this study, we show that KDM6B is highly expressed in neuroblastoma and its genomic locus is broadly marked with transcriptionally active histone modifications and transcription factor binding." (PMID 34893606, 2021). "Nevertheless, the impact of KDM6B inhibition on E2F pathways was more dramatic in MYCN-amplified neuroblastoma cells." (PMID 34893606, 2021). "Here the authors show that KDM6B regulates CDK4/6-pRB-E2F pathway through H3K27me3-dependent enhancer-promoter interactions in neuroblastoma." (PMID 34893606, 2021).
neuroblastoma (continued). "In summary, KDM6B is highly expressed in human neuroblastoma and its genomic locus is epigenetically modified for active gene transcription, which is distinct from its paralogs KDM6A and UTY." (PMID 34893606, 2021). "Our investigation provides evidence in support of this model, revealing an anti-tumorigenic activity of KDM6B in neuroblastoma cells by inducing neuronal differentiation." (PMID 30631055, 2019). "In agreement with the genetic evidence, overexpression of KDM6B in several neuroblastoma cell lines induced neuronal differentiation characterized by extensive neurite outgrowth." (PMID 30631055, 2019). "Taken together, these data provide evidence for KDM6B as a direct transcriptional target gene of HOXC9 in RA-induced neuronal differentiation of neuroblastoma cells." (PMID 30631055, 2019). "In neuroblastoma cell lines, KDM6B depletion promotes cell proliferation, whereas KDM6B overexpression induces neuronal differentiation and inhibits cell proliferation and tumorgenicity." (PMID 30631055, 2019). "In this report, we present evidence for KDM6B being an epigenetic activator of neuroblastoma cell differentiation." (PMID 30631055, 2019). "Collectively, these results reveal a growth-inhibitory and anti-tumorigenic function of KDM6B in neuroblastoma cells." (PMID 30631055, 2019). "We used shRNA lentiviral constructs to reduce KDM6B mRNA and protein expression in neuroblastoma cell lines with inducible HOXC9 expression." (PMID 30631055, 2019). "Here we report that the histone H3 lysine 27 demethylase KDM6B is an epigenetic activator of neuroblastoma cell differentiation." (PMID 30631055, 2019). "KDM6B mRNA expression is downregulated in poorly differentiated high-risk neuroblastomas and upregulated in differentiated tumors, and high KDM6B expression is prognostic for better survival in neuroblastoma patients." (PMID 30631055, 2019). "Collectively, these findings suggest that high levels of KDM6B initiate a neuronal differentiation program in neuroblastoma cells by conferring an epigenetically active chromatin state to neuronal genes for transcriptional activation." (PMID 30631055, 2019). "Collectively, these findings suggest an onco-suppressor function of KDM6B in neuroblastoma pathogenesis by promoting differentiation." (PMID 30631055, 2019). "Given that high KDM6B expression is indicative of better prognosis for neuroblastoma patients, we investigated the effect of high KDM6B expression on neuroblastoma cell proliferation and tumorigenicity." (PMID 30631055, 2019). "To explore whether alternative targeting of the DNA damage response by inhibiting MDM2 could also be synergistic with KDM6B inhibition, we treated five different neuroblastoma cell lines with the combination of GSK-J4 and Nutlin-3." (PMID 40253363, 2025). "Moreover, KDM6B has also been demonstrated to promote neuroblastoma cell differentiation by removing the repressive chromatin marker H3K27me3." (PMID 39239542, 2024). "However, KDM6B inhibits tumorigenesis via removing H3K27me3 to induce neuronal differentiation in neuroblastoma." (PMID 35783266, 2022). "Jude) also showed KDM6B expression was among the highest in neuroblastoma." (PMID 34893606, 2021). "The broad occupation of H3K4me1 and H3K27Ac across the whole locus of KDM6B indicates that a super-enhancer may regulate the expression of KDM6B in neuroblastoma." (PMID 34893606, 2021). "With this approach, we found that genes downregulated by KDM6B knockdown in neuroblastoma cells overlapped significantly with the transcriptomes downregulated by palbociclib, a specific CDK4/6 inhibitor that acts upstream of the E2F pathway in cell cycle regulation." (PMID 34893606, 2021). "The H3K27me2/me3 histone demethylase KDM6B is essential to neuroblastoma cell survival." (PMID 34893606, 2021).
neuroblastoma (continued). "The genetic and pharmacologic KDM6B inhibition results in a predominant reduction of the E2F transcriptome and MYC, which may account for the therapeutic effect of KDM6B blockade in neuroblastoma." (PMID 34893606, 2021). "Thus, our studies reveal that KDM6B regulates the oncogenic CDK4/6-pRB-E2F pathway in MYCN-amplified neuroblastoma, revealing a mechanism of regulation of the E2F transcriptome by an epigenetic modulator." (PMID 34893606, 2021). "The histone demethylase KDM6B is reported to be essential for neuroblastoma cell survival." (PMID 34893606, 2021). "We also demonstrate that E2F target genes can act as biomarkers for sensitivity to KDM6B inhibitors in neuroblastoma and that this may well be predictive for other MYC-driven tumors." (PMID 34893606, 2021). "This notion suggests that targeting KDM6B might offer a strategy to selectively activate differentiation of neuroblastoma cells." (PMID 30631055, 2019). "Similarly, ectopic expression of human KDM6B in mouse neuroblastoma sphere-forming cells resulted in a marked inhibition of cell growth." (PMID 30631055, 2019). "Finally, in a panel of neuroblastoma cell lines, we show that KDM6B depletion enhanced cell proliferation, whereas KDM6B overexpression induced neuronal differentiation and inhibited the proliferation and tumorigenicity of neuroblastoma cells." (PMID 30631055, 2019). "Thus, mouse neuroblastoma stem-like cells express significantly lower levels of Kdm6b compared to their more differentiated primary tumor cells." (PMID 30631055, 2019). "Moreover, higher KDM6B expression is correlated with higher expression of genes that promote neuronal differentiation and is prognostic for better survival in neuroblastoma patients." (PMID 30631055, 2019). "Thus, GSK-J4 phenocopied KDM6B depletion in neuroblastoma cells and, therefore, its therapeutic effect may be mediated through inhibition of KDM6B." (PMID 34893606, 2021). "Thus, our data and that from other studies indicate that a network composed of MYCN, E2F, PRC2, and KDM6B regulates cell proliferation and differentiation of neuroblastoma, highlighting the importance of KDM6B in coupling the two essential features of cancer cells." (PMID 34893606, 2021). "In addition, we show that KDM6B functions downstream of the retinoic acid-HOXC9 axis in inducing neuroblastoma cell differentiation: KDM6B expression is upregulated by retinoic acid via HOXC9, and KDM6B is required for HOXC9-induced neuroblastoma cell differentiation." (PMID 30631055, 2019). "We then compared the RNA-seq transcript counts of KDM6B, KDM6A, and UTY in three large neuroblastoma cohorts and found that expression of KDM6B was significantly higher than that of KDM6A or UTY." (PMID 34893606, 2021). "Taken together, genetic and pharmacologic inhibition of KDM6B predominantly leads to downregulation of the pRB-E2F transcriptional program, particularly in MYCN-amplified neuroblastoma cells." (PMID 34893606, 2021). "Notably, depletion of KDM6B led to MYCN and C-MYC reduction in neuroblastoma cells." (PMID 34893606, 2021). "Also, KDM6B knockdown did not induce KDM6A in neuroblastoma cells." (PMID 30631055, 2019). "We also found that levels of KDM6B expression, but not KDM6A or UTY, in neuroblastoma cell lines were among the highest, across 40 different cancer lineages." (PMID 34893606, 2021). "To investigate the molecular function of KDM6B in neuroblastoma, we performed RNA-seq followed by gene set enrichment analysis (GSEA) after knockdown of KDM6B in MYCN-amplified (BE2C and KELLY) and MYCN-non-amplified cells (SK-N-AS, SK-N-FI)." (PMID 34893606, 2021). "We have previously shown that KDM6B, but not KDM6A or UTY, is essential for neuroblastoma cell survival." (PMID 34893606, 2021).
neuroblastoma (continued). "We noticed that HOXC9 knockdown alone led to a significant decrease in KDM6B mRNA levels in the absence of RA treatment, indicating an essential role of HOXC9 in maintaining the steady-state level of KDM6B mRNA expression in neuroblastoma cells." (PMID 30631055, 2019). "In addition, immunoblot analysis revealed that overexpression of KDM6B, but not its mutant, increased NEFM protein levels in neuroblastoma cells." (PMID 30631055, 2019).
ovarian carcinoma (11 papers, 2018 to 2025). A malignant neoplasm originating from the surface ovarian epithelium. "KDM6B promoted EMT in the SKOV-3 ovarian cancer cell line and directly activated HER2 gene transcription." (PMID 34991274, 2018). "KDM6B is considered a tumor suppressor gene recurrently down-regulated in pancreatic adenocarcinoma, while reported to exhibit oncogenic properties in ovarian cancer." (PMID 33827048, 2021). "Moreover, KDM6B was also overexpressed in ovarian cancers at both protein and mRNA levels and its expression was associated with invasion, metastasis, and low overall survival." (PMID 34991274, 2018). "Moreover, EZH2 and KDM6B were frequently both overexpressed and associated with EMT, invasion, migration, or metastasis in the same cancer types, such as ovarian cancers or clear cell renal cell carcinomas." (PMID 34991274, 2018). "Loss of KDM6B expression had a negative effect on ERβ function as a ligand-dependent inhibitor of ovarian cancer cell growth." (PMID 29422491, 2018). "We studied the dependence of ERβ function on the presence of KDM6B and SIRT1 in human ovarian cancer cells in vitro." (PMID 29422491, 2018). "In ovarian cancers, HER2 (human epidermal growth factor receptor 2, a receptor involved in proliferation, migration, and survival) and KDM6B expressions were correlated to poor prognosis and a low survival rate." (PMID 34991274, 2018).
gastric cancer (10 papers, 2019 to 2025). A primary or metastatic malignant neoplasm involving the stomach. "The results of clone formation and transwell assays showed that the addition of the CXCL12/CXCR4 signaling pathway by the inhibitor, AMD3100, reverses the increase in the proliferation and migration of gastric cancer cells that was caused by KDM6B ectopic expression." (PMID 36564369, 2022). "Since H. pylori infection is a major risk factor for the development of gastric cancer, we explored whether the expression of KDM6B was associated with H. pylori infection." (PMID 36564369, 2022). "pylori infection, correlated with elevated KDM6B expression in gastric cancer patients and in vitro cell lines." (PMID 40940894, 2025). "The shRNA-mediated KDM6B depletion led to reduced tumor volume and weight in gastric cancer xenograft mice." (PMID 40940894, 2025). "In this study, we found that KDM6B is highly expressed in gastric cancer tissues through the analysis of gastric cancer datasets and clinical samples." (PMID 36564369, 2022). "The results showed that KDM6B promotes the proliferation and metastasis of gastric cancer cells in vitro and in vivo, and that this effect depends on its enzymatic activity." (PMID 36564369, 2022). "We performed RT-qPCR on 20 pairs of gastric cancer tissues and adjacent tissues that were collected from the clinic, and the results showed that KDM6B expression was upregulated in gastric cancer." (PMID 36564369, 2022). "KDM6B was found to promote the proliferation and metastasis of gastric cancer cells in vitro and in vivo via CXCR4." (PMID 36564369, 2022). "In conclusion, we experimentally confirmed that KDM6B has an oncogenic function in gastric cancer and that it can be used as a potential target for gastric cancer therapy." (PMID 36564369, 2022). "In this study, we found that KDM6B was highly expressed in human gastric cancer samples and correlated with poor prognosis in gastric cancer patients." (PMID 36564369, 2022). "The results of immunohistochemical staining further confirmed that KDM6B expression is elevated in gastric cancer." (PMID 36564369, 2022). "The results showed that KDM6B knockdown reduces the number of hepatopulmonary metastatic nodules in gastric cancer cells compared with that in the control group." (PMID 36564369, 2022). "The analysis of the corresponding receiver operating characteristic (ROC) curve showed that KDM6B had a good performance in distinguishing gastric cancer tissues from adjacent tissues, as reflected by the area under the curve (AUC) which was 0.950." (PMID 36564369, 2022). "Since the occurrence of metastasis is a major feature of gastric cancer progression, we explored the biological function of KDM6B in gastric cancer cells’ migration." (PMID 36564369, 2022). "We first analyzed the expression of KDM6B in the GEPIA and dataset GSE13911 and found that KDM6B was highly expressed in gastric cancer tissues compared with that in normal or adjacent tissues." (PMID 36564369, 2022). "Western blot analysis also showed that the protein expression level of KDM6B in gastric cancer tissues is significantly higher than that in the corresponding adjacent tissues." (PMID 36564369, 2022). "In gastric cancer, miR-941 was also observed to be downregulated, possibly targeting KDM6B and TAO kinase 1 (TAOK1) to inhibit cell proliferation, migration and invasion." (PMID 32742479, 2020). "All of these results revealed that KDM6B promoted gastric cancer cells’ migration in vivo." (PMID 36564369, 2022). "To identify the downstream target genes of KDM6B in gastric cancer, we compared differentially expressed genes between MKN-45 and MKN-45 cells following KDM6B knockdown using transcriptome sequencing and identified a series of upregulated and downregulated genes." (PMID 36564369, 2022). "In conclusion, these results strongly suggest that KDM6B has an oncogenic role in gastric cancer." (PMID 36564369, 2022).